AR (androgen receptor)
Diseases named in the same sentence as AR in open-access papers (continued):
Sharing a sentence is not in itself a finding about the gene and the disease.
prostate carcinoma (continued). "However, selective androgen receptor modulators (SARMs) and AR antagonists have been developed and applied in fields such as prostate cancer and metabolic disorders." (PMID 40777854, 2025). "Similarly, in organoid models of prostate cancer and laryngeal squamous cell carcinoma, activating the androgen receptor (AR)/GPX4 axis and inhibiting endoplasmic reticulum oxidoreductase 1 alpha (ERO1α) have both led to improved therapeutic outcomes." (PMID 40427552, 2025). "As an alternative, we developed CBPD-409, a potent, orally bioavailable PROTAC degrader that selectively targets p300/CBP, exhibiting favorable pharmacokinetics and preferential cytotoxicity in AR-driven prostate cancer over normal prostate and other tumor types." (PMID 41044247, 2025). "Taken together, targeting the HSP family of molecular chaperones is a valid therapeutic approach to overcome persistent AR signaling in advanced prostate cancer, although concerns remain about the therapeutic window and tolerability of such HSP-targeting strategies." (PMID 39787247, 2025). "Notably, IKBKE has emerged as a therapeutic target for advanced prostate cancer due to its role in inhibiting resistance to androgen receptor-targeted therapies, as well as its effects on proliferation, migration, and colony formation." (PMID 41378297, 2025). "The key references of androgen and androgen receptor in prostate cancer and bladder cancer." (PMID 40007149, 2025). "The current literature clearly demonstrates the role of certain PTMs in various serious diseases; for example, ubiquitination of the androgen receptor (AR) is recognized as a crucial regulatory factor in the development of various tumors, including prostate cancer." (PMID 40559211, 2025). "Mutations in AR interacting proteins have been identified in prostate cancer, but the composition of the AR transcriptional complex required for masculinization during human embryogenesis is largely unknown." (PMID 41249932, 2025). "The role of AR in protein translation may elucidate a potential mechanism through which AR contributes to prostate cancer progression by promoting YAP translation." (PMID 39963114, 2025). "Notably, only a subset of AR enhancers were co-occupied by p300 in prostate cancer cells, which was deterministic of stronger transcriptional activation, evidenced both by higher accessibility and subsequent recruitment of the Mediator and Pol II complexes." (PMID 41044247, 2025). "Targeting AR could enhance ferroptosis in prostate cancer cells, especially for cases resistant to conventional therapies." (PMID 40082405, 2025). "Having demonstrated that NXP800 has growth inhibitory effects in AR-dependent and AR-independent prostate cancer models, we next investigated further the effects of the drug by performing RNA-seq on VCaP, LNCaP95, and 22Rv1 prostate cancer cells subsequent to NXP800 treatment." (PMID 39787247, 2025). "Clinically, AR agonists such as testosterone are used to treat hypogonadism and muscle wasting diseases, while AR antagonists like bicalutamide and enzalutamide are employed in the treatment of prostate cancer." (PMID 40926269, 2025). "Activation of the androgen receptor (AR) is an important mediator of prostate cancer pathogenesis." (PMID 40149370, 2025). "Moreover, dihydrotestosterone promotes the transcription of TRAIL genes via AR signaling, enhancing macrophage cytotoxicity against prostate cancer cells." (PMID 40303343, 2025). "Its role in multiple cancers is currently being explored, including prostate cancer, in which it may play a role in resistance to AR inhibition." (PMID 40405591, 2025). "Additionally, this study reveals that LTFe-LTF axis exerts tumor-suppressive effects in primary prostate cancer, while also demonstrating that its expression is repressed by AR." (PMID 40082405, 2025). "The AR signaling pathway plays a pivotal role in the pathogenesis of prostate cancer." (PMID 39963114, 2025).
prostate carcinoma (continued). "Given its central role in ligand-mediated activation along with its well-characterised structure, the LBD has historically been a primary focus for drug discovery in prostate cancer, as its inhibition effectively suppresses AR-driven transcription and tumour progression." (PMID 41374958, 2025). "Collectively, these efforts may establish natural products as lead compounds to modulate AR signaling for prostate cancer prevention and treatment." (PMID 41020902, 2025). "DOT1L also cooperates with androgen receptor (AR) to upregulate Myc in AR-positive prostate cancer." (PMID 41299712, 2025). "Although androgen receptor (AR)-targeted therapies, such as enzalutamide, initially improve outcomes of prostate cancer (PCa) patients, resistance inevitably develops, partly driven by prostate cancer stem-like cells (PCSCs)." (PMID 41419457, 2025). "By employing artificial intelligence-assisteddrug design, thegroup led by Lei Li developed Se-AR PROTAC, a peptide-baseddegrader capable of degrading AR by forming a ternary complex withthe von Hippel–Lindau (VHL) E3 ligase, with a DC50 of 693 nM in AR-positive prostate cancer cells." (PMID 41255358, 2025). "In turn, it is tempting to speculate that the upregulation of TCF19 upon treatment with ADT or AR inhibitors could represent a first adaptive response that would support prostate cancer cell function and the eventual acquisition of aggressive features." (PMID 40952912, 2025). "In prostate cancer, alterations in AR signaling promote tumor initiation and progression." (PMID 41468516, 2025). "Likewise, soy-derived isoflavones such as genistein and daidzein have demonstrated anticancer activity by modulating estrogen and androgen receptor pathways critical in prostate cancer development." (PMID 40143065, 2025). "Androgen receptor inhibitors (ARIs) are approved for the treatment of advanced prostate cancer; however, some patients may experience symptoms and side effects that hinder their physical functioning." (PMID 39450762, 2025). "As the androgen receptor (AR) plays an important role in the progression of prostate cancer, mediating the effects of androgens on cellular proliferation and survival, a systemic lowering of androgen levels through androgen deprivation therapy (ADT) is the first‐line treatment." (PMID 40558023, 2025). "AR can upregulate epidermal growth factor receptor expression in prostate cancer cells." (PMID 39917165, 2025). "Recent research on regulatory RNAs abnormally expressed in many tumors, has revealed that the LncRNA HOTAIR may stabilize AR protein levels and promote androgen-independent AR signaling, as has been previously observed in prostate cancer models." (PMID 41373752, 2025). "Prostate cancer (PC) arises as an androgen receptor–driven (AR-driven) disease." (PMID 40553569, 2025). "For example, studies in prostate cancer, renal cell carcinoma, liver cancer, and breast cancer have shown that AR activation can suppress cell proliferation, migration, and metastasis or induce apoptosis and differentiation programs counteracting malignant phenotypes." (PMID 39744510, 2025). "To explore whether AR inhibition could reverse this effect, we treated prostate cancer cells with the anti-AR drug enzalutamide (ENZ)." (PMID 40082405, 2025). "Androgen receptor (AR) signaling is central to prostate cancer progression." (PMID 40568370, 2025). "To investigate the clinical relevance of SLC22A3 downregulation in prostate cancers, we knocked out SLC22A3 in the prostate cancer C4-2 cell line to assess drug sensitivity to two clinically used anti-prostate cancer drugs, Enzalutamide (AR inhibitor) and JQ1 (BRD4 inhibitor)." (PMID 39858458, 2025). "This increased AR dependence suggests that OMPC may be more responsive to androgen-deprivation therapy (ADT) compared to polymetastatic prostate cancer, where AR-independent mechanisms and resistance pathways frequently emerge." (PMID 40282432, 2025).
prostate carcinoma (continued). "Since LNCaP and 22Rv1 are both androgen receptor (AR)-dependent prostate cancer cells, we also selected the AR-independent cell line PC3 for comparative studies in our subsequent experiments, as PC3 requires less drug concentration to achieve similar effects, making it more drug-sensitive." (PMID 40066333, 2025). "Interestingly, ETS factors have been shown to markedly enhance the chromatin occupancy of androgen receptor and reprogram its cistrome in prostate cancer cells, resembling the effect of hypoSUMOylation on GR cistrome in B-ALL cells." (PMID 39953147, 2025). "While effective targeting of the AR and androgen axis remains the cornerstone of therapy, several precision-based therapies have been developed on the basis of the molecular alterations enriched in prostate cancer." (PMID 39919177, 2025). "Both in vitro and in vivo studies demonstrated that these AUTOTACs (e.g., PBA-1105, Anle138b-F105) effectively targets the androgen receptor (AR) in prostate cancer cells and methionine aminopeptidase 2 (MetAP2) in glioblastoma cells, showcasing its powerful degradation capabilities." (PMID 40008135, 2025). "However, all strains except LNCaP_APIPC retained a phenotype classification of androgen receptor active prostate cancer (ARPC)." (PMID 40956611, 2025). "Apalutamide, a selective androgen receptor antagonist, is a new treatment for prostate cancer." (PMID 40905521, 2025). "Prostate cancer cells exploit this pathway, leveraging AR signaling to sustain relentless growth." (PMID 40227610, 2025). "Prostate cancer cell growth heavily dependent on heightened androgen receptor (AR) signaling." (PMID 41415713, 2025). "In contrast, AR-positive prostate cancer cells fail to express the cytokine." (PMID 39858071, 2025). "CMV abundance in prostate epithelia increased with age, and CMV+ prostate cancer cells had higher levels of AR protein compared to uninfected cancer cells, findings that suggest that the effects of CMV we identified in vitro are operational also in humans in vivo." (PMID 40493023, 2025). "New trials are currently evaluating the role of perioperative androgen receptor–targeted therapy or Lu-labeled PSMA radioligands in locally advanced/cN1 prostate cancer, which might also lead to a change in treatment algorithms." (PMID 41322961, 2025). "Taken together, our in vitro and in vivo efficacy data demonstrate that targeting p300/CBP proteins for degradation using CBPD-409 represents a promising therapeutic strategy for advanced AR-dependent prostate cancer while exhibiting minimal on or off-target toxicity." (PMID 41044247, 2025). "Taken together, our findings elucidate a critical KMT2D/G3BP1/SPOP/AR regulatory axis in prostate cancer progression and propose that targeted inhibition of histone methylation in combination with anti-androgen therapy represents a promising strategy for the management of advanced prostate cancer." (PMID 41247636, 2025). "Additionally, retinoids can reduce the invasiveness of prostate cancer cells by regulating the activity of matrix metalloproteinases (MMPs) and affecting androgen receptor-related (AR) signaling pathways." (PMID 40362574, 2025). "We and others have identified other members of the pluripotent stem cell transcriptional circuitry as being important AR-regulated oncogenes in prostate cancer, including SOX2 and NANOG; however, we rarely see these co-expressed in cancer, or in particular, expressed with OCT4." (PMID 39858088, 2025). "Furthermore, it was originally utilized to treat advanced prostate cancer because of its capacity to block the androgen receptor (AR) and thereby lower serum testosterone levels." (PMID 40573283, 2025). "Furthermore, androgen stimulation induces unique chromatin binding events in AR-expressing CAFs, altering cytokine production and promoting prostate cancer cell migration through paracrine signaling." (PMID 40008000, 2025).
prostate carcinoma (continued). "Ligand interactions with the androgen receptor as a prostate cancer target marker (PDB ID: 1r4i)." (PMID 39980567, 2025). "Novel, potent androgen receptor (AR) pathway inhibitors (ARPIs) such as enzalutamide (enza), abiraterone, apalutamide, and darolutamide are commonly used in the treatment of men with prostate cancer." (PMID 40624104, 2025). "Additionally, another study indicated that TRAF4 plays a significant role in desmoplasia-resistant prostate cancer, a condition that presents a major clinical challenge, where the androgen receptor (AR) remains a key oncogenic factor." (PMID 40771930, 2025). "We found that CWR22Rv1 cells express lower level of CRBN compared with VCaP and other AR-positive prostate cancer cell lines, which may account for the higher DC50 observed in CWR22Rv1." (PMID 41237749, 2025). "For instance, AR phosphorylation, influenced by various protein kinases, can result in abnormal phosphorylation due to the abnormal activity of these kinases, potentially making the AR overly sensitive to low concentrations of androgens and thus promoting resistance in prostate cancer cells." (PMID 41079787, 2025). "This multi-target approach contrasts with AR-focused therapies and may offer therapeutic advantages, particularly in treatment-resistant prostate cancer subtypes." (PMID 40429793, 2025). "Notably, while AR signaling inhibition is a cornerstone of prostate cancer therapy, compensatory mechanisms driving disease progression remain poorly understood." (PMID 40082405, 2025). "In addition, the murine cell lines RM1, RM2, and RM9, developed by the Thompson group and deposited with the American Type Culture Collection (ATCC) in 1995, are AR-expressing, mesenchymal-like mouse prostate cancer cell lines." (PMID 40709190, 2025). "Notably, emerging evidence has expanded the scope of androgen receptor (AR)-mediated immune modulation beyond prostate cancer to other malignancies such as melanoma." (PMID 41179298, 2025). "These insights underscore the need for further research on the therapeutic potential of ALD against PCa and inspired our investigation into its ability to trigger apoptosis in prostate cancer cells by disrupting AR signaling and other critical survival pathways." (PMID 39980567, 2025). "Fungal extracts were prepared from 7 strains of C. comatus by using ethyl acetate (EA), hexane (H), chloroform (C), and ethanol (E) and tested against human MDA-kb2 breast carcinoma, DU-145, and PC-3 AR-independent and LNCaP androgen-dependent prostate cancer cell lines." (PMID 39852473, 2025). "Additionally, stage-specific regulatory networks in ccRCC and CHAC1-androgen receptor crosstalk in prostate cancer warrant deeper mechanistic dissection." (PMID 40860820, 2025). "While this is not established in ACC tumors, de novo steroidogenesis has been shown to increase after treatment of androgen receptor–positive prostate cancer cells with IGF-2 via upregulated expression of steroid acute regulatory protein (StAR) as well as other steroidogenic enzymes." (PMID 40270996, 2025). "AR gene amplification is a central mechanism by which prostate cancer develops resistance to NHT." (PMID 41079787, 2025). "However, prostate carcinoma research has been challenged by the difficulty of propagating prostate carcinomas ex vivo that retain AR signaling and the attendant neoplastic phenotypes that are commonly observed in patients." (PMID 40956611, 2025). "Therefore, down-regulating SOX2 expression in prostate cancer cell lines can markedly improve their sensitivity to androgen receptor signaling inhibitors." (PMID 39976818, 2025). "In prostate cancer, AR splice variants lacking the ligand-binding domain are well recognized and drive therapy resistance, but the existence and function of AR isoforms in melanoma remain unexplored." (PMID 40940929, 2025).
prostate carcinoma (continued). "By integrating spatial transcriptomics with multiplexed IF, this study revealed spatially distinct neuroendocrine (NE) cell populations emerging from KRT8+ luminal progenitors, which transit into heterogeneous ASCL1+ NE prostate cancer (NEPC) regions resistant to androgen receptor inhibitors." (PMID 40677104, 2025). "Interestingly, however, as a carcinogen in prostate cancer, the continuous activity of the AR can lead to the G1 phase arrest of prostate cancer cells and induce the senescence of cancer cells, thereby exerting an anticancer effect." (PMID 40729027, 2025). "Metabolites related to phospholipid metabolism, including glycerophosphorylcholine (GPC) and glycerophosphoethanolamine, were observed to decrease in the castration-resistant prostate cancer cells following treatment with androgen receptor (AR) activation inhibitors." (PMID 40636699, 2025). "Meanwhile, we discovered that A-T might inhibit the proliferation of prostate cancer cells by binding to AR." (PMID 41357585, 2025). "The AR is a member of the nuclear hormone receptor family and a hormone regulated transcription factor that controls the proliferation and differentiation of the normal prostate and also prostate cancer." (PMID 40072554, 2025). "Of note, TRIM24 has known oncogenic roles in ERα and AR signaling in breast and prostate cancer, respectively, although it remains unclear whether the CoREST complex plays a part in these roles." (PMID 40479062, 2025). "Notably, combining L14‐8 with low dosages of AR antagonists, such as enzalutamide and darolutamide, significantly enhanced their anti‐tumor activity in the AR‐positive prostate cancer cell models." (PMID 40536697, 2025). "Continued research and development of LLS30-based therapies is essential to devise effective strategies against drug resistance, addressing the specific mechanisms driving resistance in high Gal-1/AR-expressing prostate cancer, and providing a targeted, personalized approach to therapy." (PMID 39941722, 2025). "Moreover, the treatment of L14‐8 in prostate cancer organoids derived from patients who underwent ADT demonstrated a significant induction of cell death compared to the AR antagonist enzalutamide." (PMID 40536697, 2025). "The androgen receptor is a major factor in the growth and progression of prostate cancer." (PMID 41281744, 2025). "The androgen receptor signaling pathway is a classic pathway that induces prostate cancer, and as prostate cancer progresses, significant changes occur in metabolic pathways, including glucose metabolism, lipid metabolism, and alterations in 1C metabolic homeostasis." (PMID 40167331, 2025). "Here, we aimed at elaborating whether matrix stiffness plays a role in prostate cancer progression, transcriptional regulation, chromatin state, and AR function in various stiffness conditions from soft to hard ECM in AR-positive prostate cancer cells." (PMID 40115748, 2025). "We hypothesize that much like the androgen receptor (AR), NKX3.1 plays a pro-differentiative, tumor suppressive role in early-stage disease and potentially acts as an oncogene in late-stage, AR-driven prostate cancer." (PMID 39858088, 2025). "For example, certain mutations may lead to the dysregulation of genes involved in AR signaling in prostate cancer." (PMID 40432836, 2025). "Several AR-target genes identified here are also involved in prostate cancer progression." (PMID 41249932, 2025). "The androgen receptor (AR) plays a key role in the tumor biology of prostate cancer." (PMID 40115018, 2025). "To explore this hypothesis, we used a potent PARP7 inhibitor, RBN2397, that eliminates AR ADP ribosylation in prostate cancer cells." (PMID 40681873, 2025). "Furthermore, R9-AR-PIP and PCNA-I1S reduce cyclin A2 expression in prostate cancer cells expressing both AR-FL and AR-Vs." (PMID 40391771, 2025).